MTOR (mechanistic target of rapamycin kinase)
Diseases named in the same sentence as MTOR in open-access papers (continued):
Sharing a sentence is not in itself a finding about the gene and the disease.
neuroendocrine carcinoma (7 papers, 2016 to 2024). A malignant neuroendocrine neoplasm composed of cells containing secretory granules that stain positive for NSE and chromogranin. "Everolimus, an oral inhibitor of mammalian target of rapamycin (mTOR), is commonly used to prevent solid organ transplant rejection and treat metastatic breast, renal, and neuroendocrine cancers." (PMID 39797229, 2024). "Our results reflect that TH588 alone efficiently decreased the survival of neuroendocrine cancer cells by PI3K-Akt-mTOR axis downregulation, increased apoptosis and oxidative stress." (PMID 28542590, 2017). "mTOR and the many proteins involved in this signaling pathway play a central role in the life cycle of neuroendocrine carcinomas." (PMID 27539383, 2016). "The hypervascularization of tumors, coupled with the frequent overexpression of growth factors and constitutive overactivation of the PI3K-Akt-mTOR signaling pathway in neuroendocrine carcinomas, provides a rationale for exploring new molecularly targeted therapeutic approaches." (PMID 38884077, 2024). "The first goal of this study was indeed to understand whether miRNAs might be active modulators of mTOR pathway in lung carcinoids as compared to high grade neuroendocrine carcinomas." (PMID 29938004, 2018). "The clinical efficacy of mTOR inhibitors in lung carcinoids – and neuroendocrine cancer in general - might be improved by identifying i) the molecular mechanisms of mTOR pathway activation in cancer cells, and - as a consequence – ii) predictive markers of response to mTOR inhibitors." (PMID 29938004, 2018).
neurofibromatosis (7 papers, 2013 to 2024). A hereditary neoplastic syndrome in which tumors grow in the nervous system. "The NF1 gene, highly related to neurofibromatosis, encodes neurofibromin, a tumour suppressor protein that acts as a negative regulator of the Ras/MAPK and PI3K/mTOR signalling pathways." (PMID 37892022, 2023). "Recent year, sirolimus, a specific mTOR inhibitor has been used for the treatment of neurofibromatosis 121,22." (PMID 34011935, 2021). "Neurofibromatosis type 1 (NF1) is a common inherited disorder caused by mutations of the NF1 gene that encodes the Ras-GTPase activating protein neurofibromin, leading to overactivation of Ras-dependent signaling pathways such as the mTOR pathway." (PMID 34576341, 2021).
neurofibromatosis type 1 (7 papers, 2015 to 2025). A clinically heterogeneous, neurocutaneous genetic disorder characterized by cafe-au-lait spots, iris Lisch nodules, axillary and inguinal freckling, and multiple neurofibromas. "The mTOR/5-HT6R signaling is also associated with neurofibromatosis type 1 (NF1), an autosomal dominant disease characterized by “café au lait” macules and tumors of the central and peripheral nervous system." (PMID 39408617, 2024). "Activation of the mTOR pathway has also been implicated in several familial cancer syndromes (tuberous sclerosis (TS), neurofibromatosis type 1 (NF1), and Hippel-Lindau diseases (VHL)) associated with the development of NETs." (PMID 28593056, 2017). "The lack of an antitumor response with sirolimus in neurofibromatosis type 1 may be caused by alternative compensatory mechanisms (e.g., feedback activation of Akt activity) following mTOR inhibition." (PMID 28288694, 2017).
peripheral nerve injury (7 papers, 2013 to 2025). Injury to a peripheral nerve. "Our results suggest that the development of neuropathic pain induced by peripheral nerve injury is associated with increased activity of mTOR and its downstream effectors in the ACC." (PMID 30032425, 2019). "Peripheral nerve injury (PNI) results in a fundamental reorganization of the translational machinery in the injured peripheral nerve such that protein synthesis is increased in a manner linked to enhanced mTOR and ERK activity." (PMID 23531341, 2013). "PKN2 has been found to regulate the AKT/mTOR pathway and promote the repair of peripheral nerve injury." (PMID 40078537, 2025). "Substantially upregulated p-S6 was found in the injured (ipsilateral) DRG at day 1 after SNI and lasted for at least 7 days (P < 0.05), consistent with elevated mTOR activity in DRGs after peripheral nerve injury." (PMID 36194480, 2022). "In conclusion, this study suggests that the mTOR pathway is a critical molecular signaling pathway regulating synaptic plasticity in the IC and mechanical hypersensitivity after peripheral nerve injury and neuropathic pain." (PMID 28377693, 2017). "Thus, after peripheral nerve injury, increased TNF‐α/FFAs activate JNK‐1 and mTOR pathways, directly promoting IRS‐1 phosphorylation at inhibitory serine sites (Ser307/Ser612/Ser616)." (PMID 41414737, 2025).
Peutz-Jeghers syndrome (7 papers, 2014 to 2025). An autosomal dominant disorder caused by pathogenic variants in the STK11 gene, characterized by hamartomatous polyps in the gastrointestinal tract, mucocutaneous pigmentation and increased risk of GI and extra-GI malignancies. "A mouse model of Peutz-Jeghers syndrome (PJS) with STK11/LKB1 inactivation showed a dramatic HIF-1α increase via the mTOR pathway." (PMID 34831355, 2021).
polymicrogyria (7 papers, 2017 to 2025). A developmental brain abnormality characterized by an excessive amount of small convolutions on the surface of the brain and cognitive dysfunction. "Individuals with mTOR-related polymicrogyria also tended to be underrepresented in the microcephalic and normocephalic groups." (PMID 37486637, 2023). "Consistent phenotypic features included extensive bilateral polymicrogyria, congenital macrocephaly and early-onset refractory epilepsy, in keeping with other mTOR-opathies." (PMID 36067010, 2023). "Regarding head MRI findings, enlargement of the ventricle, polymicrogyria, and white matter abnormalities were observed in all patients with AKT3 or PIK3R2 mutations, and seemed indicative of mTOR pathway involvement." (PMID 28086757, 2017). "The involvement of mTOR pathway has been proved in FCD, in polymicrogyria, and in the TSC manifestations." (PMID 40740850, 2025).
Premature ovarian insufficiency (7 papers, 2022 to 2025). Amenorrhea due to loss of ovarian function before the age of 40. "On the other hand, in vitro fragmentation and controlled inhibition of Hippo (combined with administration of PI3K/Akt/mTOR activators) can promote the growth of preantral follicles in patients with primary ovarian insufficiency." (PMID 36294452, 2022). "mTOR is overactivated in the peripheral blood cells of women with premature ovarian insufficiency." (PMID 36707068, 2023).
salivary gland cancer (7 papers, 2011 to 2023). A primary or metastatic malignant neoplasm that affects the major or minor salivary glands. "The upregulation of mTOR activity is commonly observed in colon, urinary bladder, and salivary gland cancers formed after dysregulated Wnt and/or PI3K signaling." (PMID 21695255, 2011). "Furthermore, partially response but no toxic effect of using mTOR inhibitor, Temsirolimus on two salivary gland cancers patients with cutaneous metastasis was reported recently, providing a strong rationale of applying mTOR inhibitor for SGT treatment." (PMID 25909167, 2015). "Interestingly, the EGFR and HER2-Akt-mTOR pathways are activated in salivary gland cancer." (PMID 26449187, 2015).
Smith-Kingsmore syndrome (7 papers, 2019 to 2024).
synucleinopathies (7 papers, 2017 to 2026). "Dysregulation of other key autophagic molecules like LC3, autophagy-related protein 7 (ATG7), or mammalian target of rapamycin (mTOR) is also a characteristic feature of α-synucleinopathies." (PMID 38203531, 2023). "Collectively, our data indicate that Nilo can induce autophagy via mTOR inhibition at early stages of α-synucleinopathy." (PMID 32299471, 2020). "Furthermore, studies outside the field of synucleinopathies, have observed that CB2 signaling can activate the PI3K/Akt and mammalian target of rapamycin (mTOR) pathways which is implicated in the autophagy-lysosome system and associated with PD progression." (PMID 39334169, 2024). "The deregulation of the mTOR-dependent pathway in synucleinopathies was underscored by the finding that mTOR protein expression levels were increased in the temporal cortex of patients with DLB in comparison to controls, in particular in neurons displaying α-syn accumulation." (PMID 28122627, 2017).
tongue cancer (7 papers, 2015 to 2025). A malignant neoplasm affecting the tongue. "Previous studies have shown that curcumin modulates PI3K/AKT/mTOR signaling in hypopharyngeal and tongue carcinomas." (PMID 41312415, 2025). "GNPs showed a better impact than GLE in tongue carcinoma therapy, causing cytotoxicity and apoptosis, potentially through the PI3K/AKT/mTOR pathway." (PMID 41039321, 2025). "Previously, we have published that treating K14-CreERtam/LSL-K-rasG12D/+ mice with rapamycin, an mTOR inhibitor, prevented the development of oral papilloma and tongue carcinomas." (PMID 35409002, 2022). "The mTOR activity was reduced in both tongue cancer cell lines upon everolimus stimulation by Western blotting." (PMID 28811537, 2017). "In vitro study, tongue cancer cells treated with everolimus, the specific mTOR inhibitor, or transfected with mTOR-mediated siRNAs dramatically attenuated the abilities of cell proliferation by MTT and BrdU assays." (PMID 28811537, 2017). "First, we used siRNA to silence endogenous mTOR expression/or activity for functional studies in tongue cancer cells." (PMID 28811537, 2017). "Taken together, these results demonstrated that mTOR expression/or activity plays a pivotal role in tumor growth of tongue cancer cells." (PMID 28811537, 2017). "Both Rictor knockdown and mTOR inhibitor inactivated the mTORC2 downstream signaling such as Akt, SGK and FOXO1, and re-sensitized tongue cancer cells to chemotherapy." (PMID 25749387, 2015). "The main findings are that PL could efficiently kill tongue cancer cells via cell cycle arrest, apoptosis, and autophagy induction through modulating PI3K/Akt/mTOR signaling." (PMID 34484337, 2021). "We next determined whether the inhibitory effect of mTOR inhibitor, everolimus, exists in 4-NQO-induced tongue cancer murine model." (PMID 28811537, 2017).
Uterine leiomyoma (7 papers, 2020 to 2026). The presence of a leiomyoma of the uterus. "The PI3K/Akt/mTOR signaling has been linked to uterine leiomyoma." (PMID 39770574, 2024). "Thus, it could be suggested that the mechanism of FH mutation c.557G>A underlies uterine leiomyomas was due to the impaired mTOR signaling and autophagy." (PMID 35163394, 2022). "IGF-1 can promote the proliferation of human uterine leiomyoma cells through the PI3K/AKT/mTOR pathway." (PMID 40428303, 2025). "Vitamin D3 produces therapeutic effects for uterine leiomyomas through its dual action of controlling TGF-β-responsive genes and its blocking effect on Wnt/β-catenin and mammalian target of rapamycin (mTOR) signaling pathways." (PMID 41514933, 2026). "We observed multiple deregulated signaling pathways, including those for IGF-1, neuregulin, mTOR, TGFB1, CTNNB1, and TNF, in the mouse uterine leiomyomas." (PMID 33244099, 2020). "The last generation of protein kinase inhibitors of the pAKT/PIC3/mTOR signal pathway, capivasertib and ipatasertib, have not been clinically tested for therapy of uterine leiomyoma apparently due to obviously high side toxicity." (PMID 37987267, 2023).
uterine sarcoma (7 papers, 2015 to 2024). "The combination of Cabozantinib and temozolomide induces autophagy by decreasing the expression of mTOR protein in uterine sarcoma." (PMID 39519229, 2024). "al identified PI3K/MTOR as a potential target in 26% of cases, which were primarily ULMS, HG-ESS, and undifferentiated uterine sarcomas." (PMID 33503190, 2021). "Hyperactivation of mTOR/AKT/PI3K and overexpression of this pathway members are frequently reported in uterine sarcoma and carcinosarcoma 5,11." (PMID 33173419, 2020). "Hyperactivation of mTOR/AKT/PI3K and overexpression of this pathway members are frequently reported in uterine sarcoma and carcinosarcoma." (PMID 33173419, 2020). "In uterine sarcoma, the combined treatment of human uterine sarcoma cell line MES-SA cells with ISL and doxorubicin significantly enhances chemosensitivity via inducing apoptosis and autophagy by inhibiting the mTOR pathway." (PMID 33401375, 2021). "Although, this pathway is considered to be one of most promising target for future therapies 5, 9, 12, none of tested mTOR inhibitors was approved by FDA to be used in treatment of uterine sarcomas and carcinosarcomas." (PMID 33173419, 2020). "Since synergistic effects of blocking HDAC and mTOR have already been described in uterine sarcoma cells, CUDC-907 may be effective in uterine sarcomas." (PMID 26576131, 2015). "Present study is aimed to assess the activity of the two mTOR inhibitors (rapamycin - RAP and sapanisertib - MLN) as a single agent and combined with gemcitabine (GEM, one of substances commonly used in systemic anticancer treatment) in uterine sarcoma and carcinosarcoma in vitro models." (PMID 33173419, 2020).
age-related macular degeneration (6 papers, 2021 to 2025). Age-related loss of vision in the central portion of the retina (macula), secondary to retinal degeneration. "In the human retinal pigment epithelium cell line, binding of α MSH to MC1R can cause the activation of Akt–mTOR signaling and diminished oxidative stress and risk of age-related macular degeneration (AMD)." (PMID 41002740, 2025). "A study has found that in the context of neovascular age-related macular degeneration (AMD), TGF-β2 plays a prominent role by inducing pericyte–myofibroblast transition (PMT) via the Smad2/3 and Akt/mTOR pathways." (PMID 38662949, 2024). "In a model of age-related macular degeneration, miR-382-5p has been described to negatively regulate PTEN and subsequently activate the AKT/mTOR pathway, whereas NR3C1 acted as a miR-382-5p sponge, consequently regulating this pathway." (PMID 35884935, 2022).
amoebiasis (6 papers, 2020 to 2025). "The significantly enriched KEGG pathways were amoebiasis, mTOR signaling pathway, phosphonate and phosphinate metabolism, glycerophospholipid metabolism, and choline metabolism in cancer." (PMID 36591476, 2022). "Enrichment analysis of the KEGG signaling pathway revealed that these variously expressed genes were significantly more abundant in Amoebiasis, Oocyte meiosis and Pyrimidine metabolism, mainly including the PI3K, AKT and mTOR pathway proteins." (PMID 36864518, 2023).
Arrhythmia (6 papers, 2018 to 2023). Any cardiac rhythm other than the normal sinus rhythm. "Patient 76654, a girl with hypoplastic bulbus oculi whose mother had arrhythmias and whose sister died at age 9 because of a pontine glioma carried the maternally inherited deletion in 1p36.22, encompassing among others the CASZ1 and MTOR genes." (PMID 37012328, 2023).
arteriosclerosis (6 papers, 2014 to 2024). A vascular disorder characterized by thickening and hardening of the walls of the arteries. "Regenerative approaches aimed at modulating mTOR network activation patterns hold promise for delaying age-related vascular diseases and treatment of accelerated arteriosclerosis in chronic metabolic conditions." (PMID 31882658, 2019). "An AKT/mTOR-dependent glycolysis axis was further suggested to regulate this differentiation process, suggesting a possible role of glycolytic metabolism in EC repair of transplant arteriosclerosis, which may further serve as a potential target in vascular diseases." (PMID 32166394, 2020).
autoimmune hepatitis (6 papers, 2019 to 2025). Hepatitis caused by autoantibodies. "Therefore, we further explored the role of Rheb/mTOR pathway in the liver of autoimmune hepatitis." (PMID 33295107, 2021). "In autoimmune hepatitis (AIH), GLS antagonists like JHU083 and DON not only attenuate T cell activation and reduce the Th1/Th17 ratio but also downregulate SLC7A5 mRNA expression, further dampening mTOR pathway activation." (PMID 40155378, 2025).
biliary tract cancer (6 papers, 2010 to 2024). "The expression of mammalian target of rapamycin (mTOR), a serine/threonine kinase, which promotes the survival and proliferation of biliary tract cancer cells, is frequently upregulated in advanced biliary tract cancers." (PMID 38685684, 2024). "Two recent early‐phase clinical trials have demonstrated that a subgroup of patients with biliary tract cancer gain benefit from treatment with the mTOR inhibitor everolimus." (PMID 28544747, 2017). "MTOR pathway relevance in biliary tract cancers is suggested by our immunohistochemical detection of activated forms of mTor and its downstream effectors in 51.3% of the cancers." (PMID 24867389, 2014). "Inhibition of mTOR signalling has demonstrated antitumour activity in individual biliary tract cancer cell lines and in a transgenic mouse model of biliary tract cancer." (PMID 28544747, 2017). "To date, clinical trials with targeted therapies for advanced biliary tract cancers have failed to produce significant benefits, and ongoing studies are exploring the combination of chemotherapy with novel MAPK/ERK Kinase (MEK) and mTOR inhibitors." (PMID 24867389, 2014).
cystic lung disease (6 papers, 2013 to 2025). "This holds true also for other cystic lung diseases like mTOR inhibition in TSC‐related LAM or Vemurafenib in pLCH." (PMID 40432300, 2025). "As of today, there is no specific treatment for BHDS-associated cystic lung disease and no reports on the efficacy of mTOR inhibitor treatment." (PMID 41465753, 2025).
Duchenne muscular dystrophy (6 papers, 2015 to 2023). Duchenne muscular dystrophy (DMD) is a neuromuscular disease characterized by rapidly progressive muscle weakness and wasting due to degeneration of skeletal, smooth and cardiac muscle. "Interestingly, we observed a significant upregulation of Hrs protein level in tibialis anterior muscle samples of the two well characterized dystrophic mouse models Duchenne muscular dystrophy (mdx model;) and the muscle-specific mTOR knockout." (PMID 34330273, 2021). "To determine if Hrs expression is modulated in regenerating muscles, we performed Western blotting analyses on tibialis anterior muscle extracts from two well characterized dystrophic mouse models Duchenne muscular dystrophy (mdx model;) and the muscle-specific mTOR knockout (mTORmKO model;)." (PMID 34330273, 2021). "Moreover, VPA activates the PI3K/Akt/mTOR pathway to ameliorate pathology of Duchenne Muscular Dystrophy in mouse and induce neuronal differentiation of NSCs." (PMID 31551670, 2019). "Based on a mouse model of Duchenne muscular dystrophy, ITGA7 was shown to cross-communicate with the Akt-mTOR-axis, leading to signal amplification and growth promotion." (PMID 29721158, 2018). "However, in Duchenne’s muscular dystrophy, impaired autophagolysosome formation has been observed and is characterized by increased p62 as well as decreased LC3-II and mTOR activation, as we observed in X-ALD." (PMID 25549970, 2015).
focal cortical dysplasia type II (6 papers, 2021 to 2025). "Focal malformations are primarily caused by somatic variants in genes associated with cell growth, particularly in the mechanistic Target of Rapamycin (mTOR) pathway for focal cortical dysplasia type 2, acquired in neuronal progenitors during neurodevelopment." (PMID 38892194, 2024).